LINC00963 (long independently transcribed non-coding RNA 963)
Diseases named in the same sentence as LINC00963 in open-access papers (continued):
Sharing a sentence is not in itself a finding about the gene and the disease.
cancer (continued). "Our results proved that approaches to downregulate LINC00963 could serve as adjuvant agents to improve treatment effects as the cancer cell survival was dramatically reduced." (PMID 32357409, 2020). "Our findings indicated that LINC00963 may be a potential treatment target to diminish metastasis and cancer recurrence." (PMID 32357409, 2020). "Indeed, it has been revealed that increased LINC00963 promoted tumorigenesis and facilitated metastasis in a variety of cancers and suppression of LINC00963 downregulated proliferation, propagating capacities and induced apoptosis of cancer cells." (PMID 32357409, 2020). "Functionally, knocking down Zeb1 in LINC00963 overexpressed cancer cells was sufficient to abolish EMT and cell mobility, demonstrating its importance in LINC00963-induced metastatic phenotypes." (PMID 36604626, 2023). "Conversely, the present study demonstrated that LINC00963 overexpression accelerated DLBCL cell apoptosis in vitro and inhibited tumor growth in vivo, providing a fresh new insight into the function of LINC00963 in cancer progression." (PMID 34112145, 2021).
tumor (16 papers, 2020 to 2025). "In summary, this study unveiled multiple previously unreported alternative splicing variants of LINC00963 and explored its potential involvement in tumor invasion and migration, possibly through mechanisms linked to super-enhancer activity." (PMID 40966274, 2025). "Our research results indicate that LINC00963 is a spliced long non-coding RNA regulated by super-enhancers, which is associated with EMT-mediated tumor progression." (PMID 40966274, 2025). "Taken together, these data suggested that LUAD cells-derived exosomal LINC00963 promoted tumor growth in vivo via driving M2 macrophage polarization." (PMID 36604626, 2023). "To understand the functional consequence of exosomal LINC00963, we focused on macrophages, one of the most abundant immune cells within tumor microenvironment." (PMID 36604626, 2023). "The inhibitory effect of LINC00963 overexpression on tumor growth in vivo was consistent with the results of our in vitro experiments." (PMID 34112145, 2021). "Compared with the siNC group, the tumor size and weight were evidently reduced by siLINC00963 (P < 0.01), but LINC00963 overexpression promoted tumor growth." (PMID 33536018, 2021). "Recent studies have revealed that LINC00963 not only affects tumorigenesis by functioning as a sponge of miRNAs, but regulates the sensitivity of tumor cells to chemotherapy and radiotherapy." (PMID 34112145, 2021). "It was also found that LINC00963 overexpression resulted in significantly delayed tumor growth in a xenograft model of DLBCL." (PMID 34112145, 2021). "LINC00963, also known as MetaLnc9, is reported to be abnormally expressed in various tumor types, and is involved in regulating the proliferation, migration and invasion of tumor cells." (PMID 34498706, 2021). "The expression of LINC00963 was decreased following LINC00963 knockdown in the excised tumor tissues." (PMID 32357409, 2020). "Histopathological analysis revealed that, compared to that of the isotype vector controls, the downregulation of LINC00963 resulted in significantly reduced incidence of tumor draining lymph nodes (TdLNs), liver, lung, and bone metastases." (PMID 32554858, 2020). "To understand whether LINC00963 critically regulates tumor metastasis in vivo, we intravenously injected A549 cells with LINC00963 overexpression or silence vector into immunocompromised nude mice." (PMID 36604626, 2023). "We further identified that Linc00963 could promote tumor growth of CRPC cells by inhibiting miR-655 and upregulating TRIM24 axis in vivo." (PMID 33643926, 2021). "This study also elucidated the regulatory network of LINC00963/miR-320a/XBP1 and its biological function in tumor development, suggesting that both LINC00963 and miR-320a could be potential therapeutic targets for the molecular targeted therapy of DLBCL." (PMID 34112145, 2021). "Functionally, LINC00963 potentiated the proliferation, colony formation, migration and invasion of CRC cells, implying that LINC00963 represents a tumor promoter in CRC, and may be a promising novel therapeutic target." (PMID 34498706, 2021). "Finally, we elucidated that Linc00963 promoted cell proliferation and tumor growth of CRPC cells in vitro and in vivo by sequestering miR-655 and then upregulating TRIM24 expression." (PMID 33643926, 2021). "Many studies have demonstrated that LINC00963 as a sponge of miRNA is involved in tumor growth." (PMID 34112145, 2021). "In vivo experiments showed that LINC00963 knockdown could reduce the tumour growth of SGC-7901-R xenografts." (PMID 34697403, 2021). "LINC00963 may merely represent a subset of tumor metastasis." (PMID 40966274, 2025). "Our experimental results also indicate that LINC00963 is a long non-coding RNA regulated by super enhancers and spliced, which is involved in EMT mediated tumor progression." (PMID 40966274, 2025). "LINC00963 achieves this through its interactions with miR-324-3P, which normally inhibits the expression of ACK1, a driver of tumor progression." (PMID 38505593, 2024).
tumor (continued). "Among them, FAM30A, HCP5, LINC00963, TMEM147-AS1, and TTTY15 indicated a worse prognosis, but LINC00342, MEG3, HCG18, and N4BP2L2-IT2 demonstrated a better tumor prognosis." (PMID 35615374, 2022). "Higher expression of LINC00963 correlated with advanced TNM stage, larger tumor size, and positive lymph node invasion." (PMID 32554858, 2020). "This study corroborates the oncogenic nature of LINC00963 in LUAD and reveals two novel mechanisms responsible for its pro-tumor activities: stabilizing Zeb1 to promote epithelial-mesenchymal transition (EMT) and delivering exosomes to induce M2 macrophage polarization." (PMID 36604626, 2023). "Interestingly, we found that Zeb1 and CD206 expressions in these xenografts changed in the pattern as if LINC00963 was altered in LUAD cells, supporting the crosstalk between tumor cells and macrophages." (PMID 36604626, 2023).
LINC00963 also shares sentences with these, for which no sentence is quoted: ovarian carcinoma (3 papers); breast tumor (2); esophageal cancer (2); autoimmune disorders (1); esophageal tumor (1); hematological cancers (1); lung adenocarcinoma (1); ovarian tumors (1); prostate adenocarcinoma (1); uveal melanoma (1).